PPARG (peroxisome proliferator activated receptor gamma)
Diseases named in the same sentence as PPARG in open-access papers (continued):
Sharing a sentence is not in itself a finding about the gene and the disease.
colon carcinoma (185 papers, 2000 to 2026). "Other pathways also give rise to cancers due to Pparγ mutations with partial loss of function or chimeric mutations such as in colon cancer, prostate cancer, and thyroid tumors where Pparγ levels were associated with tumor grade and invasive ability." (PMID 34195082, 2021). "Evidence for PPARγ as a tumor growth inhibitor includes the detection of heterozygous PPARγ mutations in colon cancer and the finding that PPARγ agonists reduce tumorigenesis in murine models." (PMID 33946495, 2021). "A side-by-side analysis of these colon-cancer associated mutants with some FPLD3-associated PPARγ mutants, shows that the colon-cancer associated mutants do not consistently display profound intra- and/or intermolecular defects." (PMID 33716977, 2021). "PPARγ mutations found in colon cancer have been reported to elicit various levels of PPARγ transcriptional activity." (PMID 33266062, 2020). "Another study reports that 8% of primary colorectal tumors harbor function-dead mutations in one allele of the PPARγ gene and emphasizes the potential role of this receptor as a therapeutic target for cancer or in designing a mouse colon cancer model." (PMID 32028670, 2020). "Taken all together, the helix H3 mutations of PPARγ LBD found in colon cancers would be loss-of-function mutations that reduce transcriptional activity of PPARγ." (PMID 33266062, 2020). "More interestingly, PPARγ R288H mutation was observed in colon cancer patients and inhibited the binding of endogenous ligands." (PMID 31581474, 2019). "PPARγ activation is associated with inhibition of cell growth in human colon cancer cell lines as well as cancer xenografts in nude mice." (PMID 30186819, 2018). "Ligand activation of PPARγ in colon cancer cell lines is associated with inhibition of cell growth, increased differentiation, and reversal of the malignant phenotype." (PMID 30186819, 2018). "PPARγ, encoded by PPARG, is involved in multiple types of cancer including colonic tumor and breast tumor." (PMID 28212608, 2017). "Treatment with baicalein has been shown to inhibit cell proliferation, induce apoptosis, activate PPARγ, and inhibit NF-κB pathway in inflammation-associated colonic cancer models." (PMID 29180692, 2017). "As far as the role played by PPARγ in cancer, the association of loss of function variants with colon cancer along with some evidence of inhibition of cell proliferation and induction of apoptosis suggest its potential anti-neoplastic effects." (PMID 28208577, 2017). "The stratified analysis revealed PPARG rs1801282 C>G polymorphism also had a tendency of decreased risk to colon cancer (CG vs. CC: adjusted OR = 0.54, 95% CI = 0.27–1.08, P = 0.083)." (PMID 29246001, 2017). "Knockdown of PSF in PPARγ-expressing DLD-1 colon cancer cell lines results in loss of the autophagic marker LC3B and a corresponding induction of apoptosis through caspase-3." (PMID 26309807, 2015). "Mutations of PPARγ in colon cancer lead to the loss of ligand binding and suppression of cell growth." (PMID 23476786, 2013). "Loss of PPARγ is implicated in colorectal carcinogenesis, while ligands for PPARγ can suppress breast carcinogenesis in experimental animal models and inhibit anchorage-dependent cell growth in colon cancer cell lines." (PMID 23875171, 2013). "It was described that 4 somatic PPARγ gene mutations resulting in reducing its function occurred in 55 sporadic colon cancers." (PMID 23024650, 2012). "Synthetic PPARγ agonists promote the development of colon tumors in mice with a mutation in the tumor suppressor APC." (PMID 20182546, 2010). "PPARγ agonists have been shown to promote mouse intestinal tumors, while loss of function mutations of PPARγ has been identified in human colon tumors." (PMID 20182546, 2010). "Loss-of-function mutations to PPARγ have been reported to be associated with increased propensity of human colon cancers although the mutation of PPARγ is very rare." (PMID 19884989, 2009).
colon carcinoma (continued). "Compatible with these findings, heteroxygous loss of PPARγ increases the susceptibility of colon and stomach into carcinogen-induced colon cancer and gastric cancer, respectively." (PMID 19884989, 2009). "In murinemodels, the expression of Pparγ has been manipulated in either an environmental or a genetic background thatdisplays enhanced susceptibility to colonic cancer." (PMID 18528521, 2008). "Although an early report indicated that loss-of-functionmutations in PPARγ were common in colon cancer, this claim has notsubsequently been confirmed." (PMID 18615192, 2008). "Several mutations and polymorphisms have beenidentified in PPARγ, such as Lys319X (truncating) and Gln286Pro, insporadic colon cancer, which are associated with loss of DNA-binding andligand-dependent transcription by the PPARγ agonist, troglitazone." (PMID 18566686, 2008). "Consistent with its possible function as a tumour suppressor gene, PPARγ has been reported to be functionally mutated in sporadic cases of colon cancer; nonetheless, the overall incidence of PPARγ mutations in human malignancies seems to be very rare." (PMID 12454768, 2002). "In addition, IFC-305, an adenosine derivative, inhibits methylation of the PPARγ promoter and up-regulates PPARγ expression, thereby reducing the risk of radiation-induced intestinal toxicity in colon cancer treatment." (PMID 39875357, 2025). "Whereas all FPLD3-associated PPARG mutations that have been reported to date lead to mutant proteins that show a consistent and profound impairment in the transcriptional activity of PPARγ, the functional effects of colon cancer-associated PPARG mutations vary considerably." (PMID 33716977, 2021). "Indeed, somatic PPARG loss-of-function mutations decrease the transcriptional activity of PPARγ by inhibiting ligand binding in sporadic colon cancer." (PMID 33266062, 2020). "In addition to colon cancer-associated mutations, PPARγ R280C and R288C found in uterine and skin cancers reduced the transcriptional activity of PPARγ and resulted in remarkably weak binding affinities for RXRα and MED1 co-activators." (PMID 33266062, 2020). "However, our results showed that the helix H3 mutations of PPARγ LBD found in colon cancers, including PPARγ C285Y, Q286P, R288H and S289C mutations, exhibited lower binding affinities for endogenous ligands such as 15d-PGJ2 and 13S-HODE." (PMID 33266062, 2020). "However, in the presence of mutation in APC gene, PPARγ has been reported to be elevated in the later stages and promote the progression of colon cancer." (PMID 24999478, 2014). "Loss of function mutations in PPARG in colon cancer may also account for variability in response to PPARγ therapy." (PMID 19125177, 2008). "It has been reported that apolymorphism in codon 12 of PPARγ is associated with colon cancer risk." (PMID 18615192, 2008). "In contrast,heterozygous loss of PPARγ increases colon cancer incidence in mice." (PMID 19043612, 2008). "Patients with large numbers of ACFare at increased risk for development of subsequent colon cancers, and it is plausible thatshort-term treatment with PPARγ agonists might result in a decrease in ACFsand a subsequent reduction in colon cancer risk." (PMID 18615192, 2008). "Therefore, in colon cancer induced byAPC mutations, it appears that activation of PPARγ by TZDspromotes tumor formation, while reduction of PPARγ genedosage has little effect on tumor formation." (PMID 18784849, 2008). "Finally, in the class of capsaicinoids, capsaicin, thespicy component of hot peppers, was shown to induce apoptosis of melanoma aswell as colon and prostate cancer cells, and was associated with activation of the PPARγ in the case of colon cancer." (PMID 18779870, 2008). "However, although PPARγ acts as a tumor suppressor in colon cancer, colon tumors with mutations in the APC gene appear to be exceptions, sincethiazolidinediones promote growth in these tumors." (PMID 17389773, 2007).
colon carcinoma (continued). "Moreover, both anti-proliferative effects of PPARγ observed in vitro and inactivating mutations in the PPARγ gene found in colon tumors provide evidence for a tumor suppressor function." (PMID 17767717, 2007). "Hence, considering the diversity of human cancer, the expression of PPARγ is possibly dependent on tissue specificity and/or the mutational events (as in the case of colon cancer) that are requisite for cancer development." (PMID 15583697, 2005). "In the Min mouse model of APC deficiency, ligands for PPARγ can increase colon tumour growth." (PMID 15583697, 2005). "Furthermore, PPARγ mutations, some of which show the lossof the transactivation ability, are found in colon cancers in humans, and thatPPARγ may be considered as a tumor suppressorgene." (PMID 18584037, 2008). "As suggested by the in vivo studies of thiazolidinedionesin min mice, use of PPARγ agonists in colon cancer prevention mayrequire identification of high-risk individuals based on genetic susceptibilityas well as aberrant gene expression and signal transduction." (PMID 19125177, 2008). "Pioglitazone (agonist of PPARG) stimulates the growth of Adenomatous Polyposis Coli (APC)-mutated HT-29 human colon cancer cells, while troglitazone enhances colon cancer in normal C57BL/6 J mice." (PMID 40500799, 2025). "Most of the findings indicate that PPARγ plays a significant place in inhibiting tumor proliferation, including colon cancer." (PMID 39875357, 2025). "Studies have demonstrated that PPARδ can promote colon cancer proliferation and migration, whereas PPARα and PPARγ retard colon cancer progression." (PMID 40675969, 2025). "Previous reports have shown that the PPARγ agonist troglitazone inhibits colon cancer metastasis by inhibiting matrix metalloproteinase-7 (MMP-7) synthesis and the adhesion of extracellular matrix (ECM) proteins." (PMID 39875357, 2025). "Previous experiments have shown that PPARγ gene and protein expression is higher in rodent colon tumors than controls, suggesting a tumorigenic role for PPARγ." (PMID 39875357, 2025). "Seetha and his colleagues found that the combination of indomethacin and juglone reduces the expression of inflammatory cytokines through the Wnt, Notch, and PPARγ pathways, thereby inducing apoptosis in colon cancer cells." (PMID 39875357, 2025). "The results suggest that DC effectively inhibits colon tumor cell proliferation, clone formation, apoptosis, and cell cycle arrest through PPARγ activation." (PMID 41019996, 2025). "In the presence of EGFR, MDM2 binds to peroxisome proliferator-activated receptor-γ (PPARγ) and modulates the ubiquitination of the PPARγ protein in colon cancer cells." (PMID 40771930, 2025). "The administration of rosiglitazone, a recognized agonist of PPARG, to colon cancer cells results in the upregulation of the tumor suppressor gene PTEN." (PMID 40500799, 2025). "Further evidence substantiates the assertion that the upregulation of PPARγ by conjugated linoleic acid impedes colon cancer cell proliferation and stimulates apoptosis via interfering with glucose metabolic pathways and NAD+ levels." (PMID 39875357, 2025). "In this experiment, we studied the anti-tumor effect of DC through inducing the PPARγ transcription activation of colon cancer cells." (PMID 41019996, 2025). "We demonstrated that ZDHHC6 promotes the synthesis of fresh fatty acids and the formation of tumors by palmitoylating and stabilizing PPARγ in colon cancer." (PMID 39148124, 2024). "In the literature, PPARG is also discussed as a tumour suppressor, especially in the early stages of colon cancer carcinogenesis." (PMID 38378472, 2024). "PPARγ agonists have been shown to inhibit the development of colon cancer, highlighting the receptor’s potential as a target for therapeutic intervention in the treatment of colorectal cancer (CRC)." (PMID 39148124, 2024).
colon carcinoma (continued). "Extending these findings, we observed dysfunction of the PPARγ program in lung and colon cancer specimens compared to DF tissues." (PMID 37816052, 2023). "In cancers, such as glioma and colon cancer, the canonical WNT/β-catenin pathway is upregulated in association with decreased PPARγ expression." (PMID 36902342, 2023). "In colon carcinoma, increased PPARβ/δ expression and/or activation of PPARβ/δ antagonized the ability of PPARγ to induce cell death." (PMID 35954274, 2022). "The activation of PPARγ by different agonists increased the frequency and size of colon tumors in C57BL/6J-APCMin/+ mice." (PMID 35954274, 2022). "It was reported that the activation of PPARγ inhibits the cell growth of different cancers, such as colon cancer, gastric cancer, and liposarcoma." (PMID 36276273, 2022). "CAV1 expression is upregulated by rosiglitazone, a peroxisome proliferator-activated receptor-gamma (PPAR-γ) ligand in colon-cancer cells." (PMID 35158857, 2022). "In the presence of EGFR, MDM2 can bind to peroxisome proliferator-activated receptor-gamma (PPARγ) and regulate the ubiquitination of PPARγ protein in colon cancer cells." (PMID 36230661, 2022). "It is reported that tumor tissues of colon cancer patients expressing PPARγ have better prognosis, which supports our prognostic factor and correlation analysis." (PMID 35600382, 2022). "In fact, such Rosi and other PPARγ agonist-induced suppressions of cell adhesion was also recognized in human colon cancer cells." (PMID 34298955, 2021). "Stimulation of cultured human colonic cancer epithelial (CaCo-2) cells with 5-ASA induced expression of PPARG and the PPAR-γ-activated gene ANGPTL4 and triggered synthesis and the nuclear localization of PPAR-γ." (PMID 33468700, 2021). "Genetic and epigenetic phenomena due to genetic alterations in other genes, like RAS, can further decrease PPARγ function in colon cancer." (PMID 33716977, 2021). "It is already known that PPARγ can suppress tumorigenesis through regulation and interaction with β-catenin, and that PPARγ agonist inhibits the development of colon cancer." (PMID 32982759, 2020). "In agreement with our in vivo experiments on Eip75B-A /- C in EB differentiation, in vitro studies identified PPARγ promoting differentiation in various colon cancer cell lines." (PMID 32773037, 2020). "In a CRC mouse model, biallelic loss of PPARγ leads to a 4-fold increase tumor incidence and reduced survival in female mice over males (ApcMin/+/PPARγ-/-), whereas males develop around three times more colon tumors with wild type PPARγ." (PMID 32773037, 2020). "SFPQ (also named as PSF) translates protein binding to a nuclear receptor PPARγ and modulate growth of colon cancer cells." (PMID 32922534, 2020). "The treatment of colon cancer by suppressing the methylation of PPARγ promoter and enhancing PPARγ expression is also underway, because the hyper-methylation of promoter regions can induce PPARγ gene silence." (PMID 32028670, 2020). "Drugs like γ tocopherol have shown to upregulate PPARG level in SW 480 colon cancer cell line attributing to the anti-cancer effect which is dependent on PPARG." (PMID 31263479, 2019). "Activation of PPARγ has been understood to induce growth arrest and differentiation markers of human colon cancer cells." (PMID 31108984, 2019). "In contrast to the anticancer effects of PPARγ agonists, PPARγ stimulation leads to the development of colon cancer in mouse models." (PMID 30729133, 2019).
colon carcinoma (continued). "The activation of autophagy and peroxisome proliferator-activated receptor gamma (PPARγ) was shown to protect colon cancer cells against apoptosis induced by the interaction between butyrate and docosahexaenoic acid (DHA) in a cell type-dependent manner." (PMID 31277291, 2019). "We found 11 candidate targets (including PPARG) for colon cancer and four potential targets for esophagitis, all of which were validated by the literature." (PMID 30846939, 2019). "Curcumin was found to activate PPARγ and suppressed the growth of both HT-29 colon cancer cells and Moser cells following inhibition of EGFR and cyclin D1 expression." (PMID 31108984, 2019). "The activation of PPARγ signal transduction pathway inhibits the HT-29 colon cancer cell growth and suppress colorectal carcinogenesis, which was observed via an in-vivo study." (PMID 31108984, 2019). "The activation of PPARγ results in growth arrest of colon carcinoma cells via induction of cell-cycle arrest or/and apoptosis." (PMID 29740162, 2018). "Despite this, many human colon cancer cell lines are “resistant” to growth inhibition by thiazolidinediones, ligands of PPARγ, and also correlate poorly with levels of PPARγ expression." (PMID 30186819, 2018). "Numerous studies have shown that PPARγ has antineoplastic actions on lung, breast, prostate, and colon cancers." (PMID 29706964, 2018). "Several studies have shown a significant reduction of PPARγ expression in cancers such as colon cancer, gastric cancers, follicular thyroid cancer, cervical carcinoma, and esophageal cancer." (PMID 29706964, 2018). "Later, we also found an alternative transcript of the PPARG (peroxisome proliferator activated receptor gamma) gene that was overexpressed in colon cancer." (PMID 28758927, 2017). "The results of subsequent meta-analysis suggested that PPARG rs1801282 C>G polymorphism was associated with decreased susceptibility of CRC, especially in Asians, colon cancer and rectum cancer subgroups." (PMID 29246001, 2017). "Mice with a heterozygous deletion of PPARγ (PPARγ+/−) have an increased tendency to develop carcinogen-induced colon cancer." (PMID 27926503, 2017). "While in subgroup analyses, we found there were significant associations between PPARG rs1801282 C>G polymorphism and decreased risk of CRC among Asians, colon cancer and rectum cancer subgroups." (PMID 29246001, 2017). "For example, PPARγ-dependent TGZ cytotoxicity was reported in lung cancer and osteoblastic cells, while PPARγ-independent cytotoxicity was observed in colon cancer, cervical cancer, and prostate carcinoma." (PMID 28673319, 2017). "To date, the role of PPARγ in the gastrointestinal tract has, in the main, been restricted to the study of inflammation and cancer, which has led to the identification of PPARγ as a promising therapeutic target in colon cancer." (PMID 27853235, 2016). "Correspondingly, APCmin/+ mice which have undergone PPARG genetic ablation demonstrate increased colon tumour growth." (PMID 27579030, 2016). "Due to the high expression level of PPARγ, the colon cancer cell SW480 was selected as a tool cell line to further investigate the effect of three phytochemical on the trans-activation of PPARγ and the regulation of OCTN2, as described in our published study." (PMID 27445823, 2016). "Mounting evidence suggests that the increase of PPARγ expression and its transcriptional activity as a target play an important role of anti-inflammation and the suppression of inflammation-driven colon cancer." (PMID 27445823, 2016). "Tumor development and cell proliferation activityof PPARγ has long been investigated and reported mostly in coloncancer cell lines, colonic tumors and normal colonic mucosa." (PMID 28246465, 2016). "Nuclear receptor PPARγ has been proven to affect metabolism in multiple tissues, and has received considerable attention for its involvement in colon cancer and inflammatory disease." (PMID 27853235, 2016).